MUC1 (mucin 1, cell surface associated)
Description:
The alpha subunit has cell adhesive properties. Can act both as an adhesion and an anti-adhesion protein. May provide a protective layer on epithelial cells against bacterial and enzyme attack. The beta subunit contains a C-terminal domain which is involved in cell signaling, through phosphorylations and protein-protein interactions. Modulates signaling in ERK, SRC and NF-kappa-B pathways. In activated T-cells, influences directly or indirectly the Ras/MAPK pathway. Promotes tumor progression.
Synonyms: MUC-1; CA 15-3; KL-6; PUM; PEM; EMA; CD227; ADMCKD; ADMCKD1; MCKD; MCD; Ca15-3; ADTKD2; H23AG; MAM6; MCKD1; MUC-1/SEC; MUC-1/X; MUC1/ZD; PEMT
Tractability: Small molecule: a structure with a bound ligand is known; it has a binding pocket of medium quality. Antibody: a drug acting on it is in phase 2 or 3 trials; UniProt places it where antibodies can reach, with high confidence; its Gene Ontology location is reachable by antibodies, with high confidence; UniProt predicts a signal peptide or a membrane-spanning region; the Human Protein Atlas places it where antibodies can reach. Other modalities: a drug acting on it is in phase 2 or 3 trials.
Gene: Protein-coding gene on chromosome 1 (155,185,824 to 155,192,916, reverse strand). Ensembl gene ENSG00000185499.
Subcellular location: Apical cell membrane; Secreted (Isoform 5); Secreted (Isoform Y); Secreted (Isoform 9); Cell membrane (Mucin-1 subunit beta); Cytoplasm; Nucleus
Subcellular location (Human Protein Atlas): Plasma membrane; Predicted to be secreted
Pathways (Reactome):
Disease: Defective C1GALT1C1 causes TNPS; Defective GALNT12 causes CRCS1; Defective GALNT3 causes HFTC
Developmental Biology: Developmental Lineage of Mammary Gland Alveolar Cells; Developmental Lineage of Mammary Gland Luminal Epithelial Cells
Immune System: Dectin-2 family; Interleukin-4 and Interleukin-13 signaling
Metabolism of proteins: O-linked glycosylation of mucins; Termination of O-glycan biosynthesis
Gene Ontology:
Molecular function: protein binding; transcription coregulator activity
Biological process: mitotic G1 DNA damage checkpoint signaling; negative regulation of cell adhesion mediated by integrin; negative regulation of transcription by RNA polymerase II; positive regulation of transcription by RNA polymerase II
Cellular component: chromatin; extracellular exosome; extracellular region; plasma membrane; vesicle; apical plasma membrane; Golgi lumen; cytoplasm; nucleus
Genetic constraint (gnomAD): Loss-of-function variants: 28 observed, 39.83 expected, observed/expected ratio (o/e) 0.7, 90% interval 0.52 to 0.96. The upper end of that interval is the gene's LOEUF score, 0.96, which puts it in group 4 of 6, group 1 being the genes least tolerant of losing a copy. Missense variants: 676 observed, 605.79 expected, observed/expected ratio (o/e) 1.12, 90% interval 1.05 to 1.19. Synonymous variants: 305 observed, 260.7 expected, observed/expected ratio (o/e) 1.17, 90% interval 1.07 to 1.29.
Gene-disease validity (ClinGen):
ClinGen rates the evidence that MUC1 causes each of these diseases.
tubulointerstitial kidney disease, autosomal dominant, 2 (autosomal dominant): Definitive.
Homologues: Orthologues: chimpanzee MUC1 (99% identical), macaque MUC1 (86% identical), mouse Muc1 (52% identical), rabbit MUC1 (52% identical), rat Muc1 (49% identical), dog MUC1 (45% identical), Caenorhabditis elegans cnp-2 (15% identical).
Diseases named in the same sentence as MUC1 in open-access papers:
MUC1 is named in the same sentence as 590 diseases in open-access papers, as found by Europe PMC text mining. Sharing a sentence is not in itself a finding about the gene and the disease. The quoted sentences say what the papers report.
breast carcinoma (764 papers, 1981 to 2026). "MPD is distinguished by Paget cells within the nipple epidermis, frequently confirmed by markers such as cytokeratin 7 (CK7) and mucin 1 (MUC1), reflecting its breast cancer association." (PMID 40230781, 2025). "Clinically, MUC1 overexpression in breast cancer patients is associated with advanced tumor stages and a poor prognosis." (PMID 39755633, 2025). "CA 15-3 is a glycoprotein fragment derived from MUC1, the latter being a protein product of the breast cancer-associated MUC1 gene." (PMID 40723883, 2025). "Quercetin also suppresses the expression of Mucin 1 (MUC1), a transmembrane glycoprotein overexpressed in breast cancer cells because of gene amplification and the loss of gene transcription and post-transcription regulatory networks." (PMID 38543147, 2024). "It has also been reported that mAb against MUC-1 can be an important diagnostic and therapeutic agent in mammary cancer." (PMID 38474142, 2024). "High expression of MUC1 was associated with the presence of axillary lymph node metastases in breast carcinoma and similarly, high expression of MUC1 was related to a significantly shorter overall survival (OS) in sinonasal adenocarcinomas." (PMID 36367122, 2023). "To target tumor-associated MUC1 on breast cancer cells, we have generated second-generation CAR MUC1 T cells with two differential costimulatory signals, that is, 41BB and CD28, and determine their immune characteristics and in vitro antitumor activities." (PMID 36457849, 2022). "Mucin 1 (MUC1) is a tumor-associated antigen expressed on a variety of epithelial adenocarcinomas, including breast cancers." (PMID 35632582, 2022). "Here, we generated second-generation CAR T cell targeting tumor-associated mucin-1 (CAR MUC1) T cells and evaluated their antitumor activity in vitro against breast cancer." (PMID 36457849, 2022). "In this present study, we generated second-generation CAR T cells targeting tumor-associated MUC1 for breast cancer and evaluated the effects of two costimulatory molecules on antitumor activities and immunophenotypes related to CAR T cell persistence." (PMID 36457849, 2022). "The high expression of abnormal MUC1 in various human cancers (such as lung cancers and breast cancers) endows itself a rank of cancer-associated antigens (TAA)." (PMID 35712073, 2022). "Transformation and the loss of polarity in breast cancer epithelial cells causes the overexpression of MUC1, which in turn induces Crumbs homolog-3 (CRB3) expression and inhibits yes-associated protein (YAP) and YAP/β-linked protein-mediated Myc expression." (PMID 34207342, 2021). "AMAP1 localizes with CBL–CIN85 complex at invadopodia to advance breast cancer cell invasion and MUC1 association with CBL–CIN85 complex at the plasma membrane and in the cytosol contributes to the progression of colon cancer." (PMID 33627783, 2021). "Nonetheless, high Siglec-8 expression was observed in luminal-like breast cancer and strongly correlated with tumor-associated epitope of MUC-1 expression." (PMID 34827170, 2021). "MUC1 is a breast cancer-associated transmembrane glycoprotein, of which the extracellular domain is formed by the repeating 20-amino acid sequence N-PDTRPAPGSTAPPAHGVTSA-C." (PMID 33738611, 2021). "Examples of this association are as follows: high levels of autoantibodies to MUC1 in patient sera are associated with favorable prognosis in a relatively small cohort of breast cancer patients." (PMID 33506656, 2021). "Overexpression of C1GalT1 by transfection in breast cancer MCF-7 cells increased the interaction of the MUC1 C-terminal with β-catenin, causing increased cancer cell migration and invasion in vitro and increased tumor growth in mice." (PMID 34944925, 2021).
breast carcinoma (continued). "The high proportion of breast cancer cases expressing MUC1, as well as its association with the two most aggressive molecular classes, indicate a substantial role in the biology of breast cancer in our cohort, and it is an indication of poor prognosis." (PMID 32377198, 2020). "Considering the factors over-expressed by MUC1-ST-induced macrophages, their functionality, transcriptome and location, it is highly likely these cells are pathogenic in breast cancer." (PMID 33149188, 2020). "The presence of MUC1-ST TAMs in primary breast cancers, a MUC1-ST TAM signature being associated with poor prognosis and its phenotype contributing to systemic features of cancer, suggest that approaches based on targeting TAMs should include this subtype." (PMID 33149188, 2020). "Analysis of 53 breast cancers demonstrated the presence of this macrophage subtype in primary breast cancers and using the top nine differentially expressed genes by the MUC1-ST-induced macrophages, we showed a significant association with poor prognosis." (PMID 33149188, 2020). "The MUC1 mucin which carries multiple O-linked glycans shows a dramatic change in glycosylation in many cancers, including breast cancers, resulting in the core protein carrying multiple sialylated tri-saccharides known as ST." (PMID 33149188, 2020). "Our in vivo data showed that MUC1 overexpression was associated with the higher growth rate of CIPp-MUC1 tumors, which suggested that MUC1 upregulation promoted the growth of canine mammary tumors in vivo." (PMID 33375426, 2020). "Principal conclusions: Tumor-associated MUC1 is a very important biomarker for breast cancer next to the traditional markers estrogen receptor (ER), progesterone receptor (PR) and HER/2-neu." (PMID 31588183, 2019). "MUC1 is a breast cancer-associated type I transmembrane heterodimer, comprised of two subunits: An α-subunit consisting of an extracellular N-terminal domain and a β-subunit composed of a transmembrane helix and a short cytoplasmic tail." (PMID 31470531, 2019). "Self-generated primary murine breast cancer cells expressing human tumor-associated MUC1 were transplanted subcutaneously in wild type and human MUC1-transgenic mice." (PMID 31588183, 2019). "Hu(TA)MUC1 is a tumor-specific antigen on breast cancer cells with an exceptionally high diagnostic and potential prognostic value/importance." (PMID 31588183, 2019). "In vitro cell studies showed strong binding to human tumor-associated MUC1 expressing breast cancer cells." (PMID 31588183, 2019). "A very promising marker to support breast cancer diagnosis and prognosis is the tumor-associated MUC1 ((TA)MUC1) 5-9." (PMID 31588183, 2019). "Increasing evidence has shown that MUC1 is also associated with the stemness of lung cancer and breast cancer." (PMID 30518424, 2018). "To investigate the association of MUC1 with p50 in human breast cancers, we collected two independent large datasets for co-expression analysis between MUC1 and p50." (PMID 29423058, 2018). "Spearman correlation analysis indicated a positive association between the expression of MUC1 and p50 in Luminal A (r = 0.25, P = 0.012) and Luminal B (r = 0.28, P = 0.03) subtype breast cancer in GSE1822 dataset." (PMID 29423058, 2018). "Results showed that MUC1 was positively associated with p50 in Luminal A and Luminal B subtypes across two independent breast cancer data sets." (PMID 29423058, 2018). "In support of our views, recent expression data analysis indicated that the expression of MUC1 is up-regulated in Pregnancy Associated Breast Cancer (PABC) tissues." (PMID 29423058, 2018). "In encoding a specific membrane glycoprotein, MUC1 is usually expressed in the epithelial female cancer subtypes (e.g., ovarian cancer and breast cancer) and regarded as the biomarker of cancer cell stemness." (PMID 29534550, 2018).
breast carcinoma (continued). "Strong binding of this antibody in EA is most likely due to a tumor associated MUC1 reduction in glycan chain length and density similar to that seen in breast cancer." (PMID 28212575, 2017). "This study adds six important findings to the previous observation that a T cell response against a single breast cancer-associated antigen, MUC-1, is induced during the first trimester of pregnancy." (PMID 29285226, 2017). "Mucins1 (MUC1) is present in healthy epithelial cells and over-expressed in ∼90 % of breast carcinomas, correlating with poor prognosis and an increased risk of metastasis." (PMID 28968987, 2017). "Similar to our previously reported data in breast cancer cells, we found that nuclear MUC1 directly associated with NF-κB p65 and occupied the promoter of NF-κB regulated genes." (PMID 29285251, 2017). "We have previously demonstrated that hypoglycosylated MUC1 in human breast cancer directly associates with NF-κB family members and acts to amplify NF-κB-regulated cytokine expression." (PMID 29285251, 2017). "Correspondingly, a single STAT responsive element has been identified within the MUC1 promoter, that when mutated both decreases MUC1 promoter activity in breast cancer cells and also abolishes stimulation by interleukin-6 and interferon-gamma." (PMID 27768738, 2016). "In a 15 year follow-up of a pilot Phase III trial of Stage II breast cancer patients treated with oxidized mannan linked to MUC1 with 5 TR, the recurrence rate was greatly reduced compared to placebo (two out of 16 patients versus nine out of 15 patients)." (PMID 27367740, 2016). "Conversely, overexpression of C1GalT1 in breast cancer cells increased association between MUC1 and β-catenin by promoting the shedding of the extracellular domain, which was correlated with increased migratory and invasive behavior." (PMID 27483328, 2016). "In MUC1 transgenic mice, sialyl-O-glycans have been shown to be associated with an enhanced growth of transplantable mammary carcinoma." (PMID 27754373, 2016). "Additional studies in breast cancer demonstrate that hypoglycosylation of MUC1 to form Tn and STn antigens results in increased association with the SH3 domain-containing kinase-binding protein 1, CIN85." (PMID 27483328, 2016). "These modified screen printed carbon electrodes were further exploited to develop a very sensitive electrochemical DNA aptamer-based biosensor to detect mucin (MUC1), a prevalent gene associated with breast cancer." (PMID 27782067, 2016). "In accordance with this concept, MUC1 has previously been reported to associate with and contribute to the development of breast cancer stem cells." (PMID 27825118, 2016). "The prognostic value of HER2 ECD combined with MUC1 in early breast cancer was shown to be valuable in identifying high-risk breast cancer patients." (PMID 26509158, 2015). "The induced antibodies were selectively directed against the tumor-associated MUC1 structures and strongly bind to breast cancer cells of the MCF-7 cell line." (PMID 26161361, 2015). "The O-linked oligosaccharides on the MUC1 shed in to serum of an advanced breast cancer (ABC) patients were analysed by HPLC." (PMID 26509158, 2015). "The presence of core 1 structure on MUC1 has been reported to associate with its recycling and protects breast cancer cells from immune surveillance." (PMID 25762620, 2015). "In human breast cancer cells, expression of sTn on MUC1 was associated with reduced cell adhesion and increased cell migration." (PMID 24592356, 2014). "The association between Siglec-9 positive immune cells and MUC1-positive tumor cells has been detected in tissues of human colon, pancreas, and breast cancer." (PMID 24592356, 2014). "Investigators reveal that MUC1 has immense potential as diagnostic or prognostic marker and as therapeutic targets in breast cancer." (PMID 24639126, 2014).
breast carcinoma (continued). "Overexpression of MUC1, as found in breast cancer cells, is also associated with resistance to apoptosis in response to genotoxic anti-cancer agents." (PMID 24770886, 2014). "The partial reverse cell polarity in breast carcinoma was reported to be associated with the decrease of immunostaining for MUC-1 and lymphatic tumor spread." (PMID 24708742, 2014). "Assays to detect the cancer-associated antigen CA15.3 (also known as MUC1) in serum are widely used for monitoring disease progression and response to therapy in some late-stage breast cancer patients." (PMID 23128437, 2013). "Our findings implicate this newly identified CIN85/MUC1 complex associated with invadopodia-related molecules in promoting the invasive and metastatic potential of breast cancer." (PMID 24072600, 2013). "Gene microarray analysis of MCF-7 breast cancer cells demonstrated that silencing of MUC1 is associated with decreases in Rab31 expression." (PMID 22792175, 2012). "The overexpression of MUC1 in human breast cancers is associated with targeting of the MUC1-C subunit to the nucleus where it interacts with ERα." (PMID 22792175, 2012). "Correlating to the presence of ICAM-1 on the MSC, breast cancer cells express cell surface-associated mucin 1 (MUC1)." (PMID 22943670, 2012). "The overexpression of MUC1 in breast cancer cells is also associated with accumulation of MUC1-C in the cytoplasm by a mechanism that likely involves retrograde trafficking during endocytosis and movement to the endoplasmic reticulum." (PMID 22792175, 2012). "Aptamers can be functional blocking aptamers such as nucleolin aptamers or target-binding aptamers such as the prostate-specific membrane antigen (PSMA) aptamer for prostate cancer and Mucin 1, the cell surface associated (MUC1) aptamer for breast cancer." (PMID 23213278, 2012). "Autoantibodies to specific cancer associated glycoforms of MUC1 are found more frequently and at higher levels in early stage breast cancer patients than in women with benign breast disease or healthy women." (PMID 21385452, 2011). "A positive test result for both MUC1 IgG and IgM abs in pretreatment serum was associated with a significant benefit in disease-specific survival in stage I and II (P = 0.0116) breast cancer patients." (PMID 24212946, 2011). "The truncated glycans carried on breast cancer-associated MUC1 include the single sugar, αGalNAc (Tn), its sialylated derivative (STn), T (Galβ1,3GalNAcα) and sialylated T." (PMID 21385452, 2011). "We have exploited the change in O-glycosylation to measure autoantibody responses to cancer-associated glycoforms of MUC1 in sera from early stage breast cancer patients." (PMID 21385452, 2011). "The MUC1 protein is overexpressed in the majority of breast cancers and is implicated in breast cancer metastasis." (PMID 21798038, 2011). "Using novel micro-arrays carrying different glycoforms of MUC1 we have demonstrated the presence of autoantibodies in the sera of a proportion of breast cancer patients that recognise MUC1 carrying specific O-linked glycans." (PMID 21385452, 2011). "We used a microarray platform of 60mer MUC1 glycopeptides, to confirm the presence of autoantibodies to cancer associated glycoforms of MUC1 in a proportion of early breast cancer patients (54/198)." (PMID 21385452, 2011). "In contrast, the presence of MUC1 autoantibodies has been associated with a reduced risk for disease progression in patients with breast cancer." (PMID 22084684, 2011). "Although the overall composition of CIC varies quantitatively even for patients with the same malignancy, MUC1 has been described as a part of CIC associated with cancer including breast carcinoma." (PMID 19715603, 2009).